KIF1A (kinesin family member 1A)
Diseases named in the same sentence as KIF1A in open-access papers (continued):
Sharing a sentence is not in itself a finding about the gene and the disease.
epilepsy (12 papers, 2017 to 2025). A brain disorder characterized by episodes of abnormally increased neuronal discharge resulting in transient episodes of sensory or motor neurological dysfunction, or psychic dysfunction. "In our study, we identified a rare mutation of KIF1A in a family with six affected patients over three generations using a panel of epilepsy-related genes and Sanger sequencing." (PMID 32174959, 2020). "Novel KIF1A mutation was the only significant molecular finding in a Chinese family with AD epilepsy (6 patients in 3 generations and diabetes in some of them but no other signs)." (PMID 32746806, 2020). "Only a handful of previous reports have related KIF1A gene mutations to epileptic seizure, and thus far, the role of KIF1A in the origin of epilepsy has received limited attention." (PMID 32174959, 2020). "According to the observation of our patients with KIF1A mutations, epilepsy may present in age-dependent stages." (PMID 37239332, 2023). "The identification of other epilepsy patients with mutations in this gene should further confirm the role of KIF1A and might provide further insights into the full clinical spectrum." (PMID 32174959, 2020). "Finally, patients with KIF1A mutations also present with epilepsy, where some forms are connected to altered voltage-gated ion channels activity." (PMID 31616253, 2019). "Using epilepsy panels and WES, we identified rare variants in several genes, including POLG, SCN1A, SCN9A, KIF1A, and CNTNAP2, which were associated with specific clinical characteristics." (PMID 40565516, 2025). "Not only this, one interesting thing to be noted is that along with KIF1A mutations, the mutations on the HUWE1 gene have also led to the expression of ASD and other conditions like epilepsy." (PMID 37259299, 2023). "The end of the stalk region contains the globular tail/pleckstrin homology domain, which recognizes vesicles and membranous organelles Thus far, limited studies have investigated the role of KIF1A in the origin of epilepsy." (PMID 32174959, 2020). "As epilepsy is also seen in complicated SPG-30, it is possible that KIF1A mutations contribute to epileptic seizures by mislocalizing and impeding SV2A function." (PMID 31616253, 2019). "KIF1A gene is localized in the cytogenic 2q37.3 band and microdeletion of chromosome 2q37 is deleted in patients suffering from 2q37 microdeletion syndrome that can be observed by intellectual disability, brachydactyly, weight gain, hypotonia, characteristic facial features, autism, and epilepsy." (PMID 37259299, 2023). "However, de novo dominant KIF1A mutations may result in a phenotypic spectrum overlapping with AR SPG30 including mental retardation, speech delay, epilepsy, optic nerve atrophy, thinning of the corpus callosum, periventricular white matter lesion and microcephaly." (PMID 33646413, 2021). "However, mutations in KIF1A have not been detected in patients with epilepsy." (PMID 32174959, 2020). "The KIF1A-related spectrum is vast, and ASD-resistant epilepsy is common in some known phenotypes." (PMID 35160058, 2022).
Cerebellar atrophy (10 papers, 2016 to 2023). Cerebellar atrophy is defined as a cerebellum with initially normal structures, in a posterior fossa with normal size, which displays enlarged fissures (interfolial spaces) in comparison to the foliae secondary to loss of tissue. "All three patients in our study with KIF1A variants who underwent brain MRI scans were found to have cerebellar atrophy, and two of these patients had serial scans showing progression." (PMID 37251230, 2023). "We report on a previously unpublished de novo heterozygous likely pathogenic KIF1A variant associated with slowly progressive complicated SPG30 and stable cerebellar atrophy on long-term follow-up, adding to current knowledge on this HSP subtype." (PMID 31796088, 2019). "WES was used to identify a novel de novo mutation in KIF1A, a known causative gene of neurodegeneration and spasticity with or without cerebellar atrophy or cortical visual impairment syndrome (NESCAVS)." (PMID 36227410, 2023).
developmental delay (10 papers, 2017 to 2026). "One patient (ID 18) with a heterozygous KIF1A variant experienced their first unprovoked seizure at the age of 44 months and also had developmental delay." (PMID 34469436, 2021). "Many variants of the KIF1A gene have been associated with neurodegenerative diseases and developmental delay." (PMID 28970574, 2017). "Notably, in Qatari 1 proband who has global developmental delay, we identified a 234 bp Del in intron 5 of KIF1A, which encodes a motor protein essential for axonal transport of synaptic vesicle precursors." (PMID 40325133, 2025). "Deleterious heterozygous mutations of KIF1A in developmental delay have been suggested to act dominant negative effects, and this could explain their phenotype more severe than that those observed in patients with recessive mutations." (PMID 28970574, 2017). "KIF1A mutations cause NESCAV syndrome (NESCAVS), a neurodegenerative disorder characterized by global developmental delay, progressive spasticity, ID, speech delay, learning disabilities and/or behavioural abnormalities." (PMID 34356170, 2021).
NESCAV syndrome (8 papers, 2019 to 2026). "Heterozygous pathogenic variants in the KIF1A gene can cause NESCAV syndrome (MIM #614255) or spastic paraplegia 30, autosomal dominant (MIM #610357)." (PMID 37405542, 2023). "Most identified KIF1A variants associated with NESCAV syndrome were heterozygous and occurred de novo." (PMID 37239332, 2023). "Variants causing autosomal dominant mental retardation type 9 or SPG30 invariably are missense variants located in the kinesin motor domain of the KIF1A protein, an important domain for ‘walking’ of the kinesin along microtubules." (PMID 31488895, 2020). "KIF1A has been recognized as a causal gene in HSAN2, SPG30, and NESCAV syndrome." (PMID 39076207, 2024). "To explore the correlation between KIF1A gene mutation and their manifestations, we examined the rare ALS-related mutations found in our research and compared them to ClinVar pathogenic variants linked to other conditions (SPG30, HSAN2, and NESCAV syndrome)." (PMID 39076207, 2024). "No overlap was seen with the KIF1A variants reported in the allelic disorders autosomal recessive hereditary sensory neuropathy IIC, autosomal dominant mental retardation type 9, or autosomal recessive SPG30." (PMID 31488895, 2020).
hereditary sensory and autonomic neuropathy type 2 (7 papers, 2016 to 2024). Hereditary sensory and autonomic neuropathy, type 2 (HSAN2) is an inherited disorder characterized by profound and universal sensory loss involving large and small fiber nerves, and marked hypotonia. "Currently, mutations in KIF1A are listed as associated with three disorders in the OMIM database: hereditary sensory and autonomic neuropathy type 2 (HSAN2) with a recessive pattern; mental retardation type 9 (MRD9) with dominant inheritance; and SPG30 with either dominant or recessive inheritance." (PMID 36284339, 2022).
optic atrophy (7 papers, 2016 to 2024). A disorder characterized by loss of optic nerve fibers. "There is a correlate in humans where mutations in KIF1A affect axonal transport and can lead to progressive neurodegeneration, including optic atrophy." (PMID 27932942, 2016). "Thus, several cases with phenotype of PEHO syndrome (Progressive encephalopathy with edema, hypsarrhythmia, and optic atrophy) and with mutated KIF1A were reported (where ‘classic’ PEHO is severe AR disorder produced by ZNHIT3 mutations)." (PMID 32746806, 2020). "Occasionally, KIF1A variants have also been linked with progressive encephalopathy with brain atrophy, progressive neurodegeneration, PEHO-like syndrome (progressive encephalopathy with edema, hypsarrhythmia, optic atrophy), and Rett-like syndrome." (PMID 37239332, 2023). "KIF1A variants have also been occasionally linked with progressive encephalopathy with brain atrophy, progressive neurodegeneration, PEHO-like syndrome (progressive encephalopathy with edema, hypsarrhythmia, optic atrophy), and Rett-like syndrome." (PMID 37239332, 2023).
amyotrophic lateral sclerosis (6 papers, 2019 to 2024). Amyotrophic lateral sclerosis (ALS) is a neurodegenerative disease characterized by progressive muscular paralysis reflecting degeneration of motor neurons in the primary motor cortex, corticospinal tracts, brainstem and spinal cord. "Mutations in the C-terminal of KIF1A (Kinesin family member 1A) may lead to amyotrophic lateral sclerosis (ALS) through unknown mechanisms that are not yet understood." (PMID 39200158, 2024).
autism (6 papers, 2015 to 2024). Persistent deficits in social interaction and communication and interaction as well as a markedly restricted repertoire of activity and interest as well as repetitive patterns of behavior. "Contrary to other studies where a haploinsufficiency of KIF1A, FARP2, HDLBP, and AGAP1 genes was cited as a possible cause for autism in 30–35% of 2q37DS, in our patients, autistic spectrum disorder was found in just one case." (PMID 36833393, 2023). "To examine the protein level of the RNAseq results in mouse CAD cells, we tested genes involved in autism risk (NLGN1), neurodegeneration (ATXN1), neurogenesis (REST), embryonic development (TLE4), and neuronal migration (KIF1A)." (PMID 26094033, 2015).
hereditary sensory neuropathy (6 papers, 2017 to 2025). "Variants in the KIF1A gene can cause autosomal recessive spastic paraplegia 30, autosomal recessive hereditary sensory neuropathy, or autosomal (de novo) dominant mental retardation type 9." (PMID 31488895, 2020).
breast carcinoma (5 papers, 2014 to 2023). "KIF1A exerts a protective effect and is significantly associated with 10-year recurrence-free survival in breast cancer patients." (PMID 37452081, 2023). "KIF1A promoter methylation was associated with breast cancer and inversely associated with DRC." (PMID 24927296, 2014). "KIF1A was reported over-expressed in ER- breast cancer cell lines MDA-MB-231 and MDA-MB-468, and contributes to their chemotherapeutic resistance." (PMID 28754978, 2017). "We demonstrated that KIF1A promoter methylation can distinguish breast cancer (BC) cases from controls in plasma and was inversely associated with DNA repair capacity (DRC) levels in a BC case control study." (PMID 24927296, 2014).
diabetes (5 papers, 2013 to 2021). "Two-way ANOVA analysis revealed a significant effect of diabetes (p < 0.01) on KIF1A mRNA levels in DRG." (PMID 29351809, 2018). "In particular, and in agreement with previous findings, diabetes induced a significant increase of KIF1A mRNA levels in males (Bonferroni post hoc analysis, p < 0.05)." (PMID 29351809, 2018). "Specifically, we showed that short-term diabetes alters both the mRNA levels and axoplasm content of KIF1A and KIF5B and axoplasm content of KIF5A and Myosin Va, but only in male animals." (PMID 29351809, 2018). "At 8 weeks of diabetes, KIF1A mRNA levels significantly increased to 2.24±0.6 of the control, as well as KIF1A protein levels in hippocampal total extracts (increase to 140.3±4.0%) compared to age-matched control animals (respectively)." (PMID 23776493, 2013). "We investigated the effect of diabetes (2 and 8 weeks duration) on KIF1A, KIF5B and dynein motor proteins, which are important for axonal transport, in the hippocampus." (PMID 23776493, 2013). "Specifically, we showed that diabetes alters the mRNA levels, and immunoreactivity of KIF1A and KIF5B motor proteins in the hippocampus of diabetic rats." (PMID 23776493, 2013). "Increased mRNA expression of KIF1A (increase to 1.92±0.6 of the control) and KIF5B (increase to 1.39±0.2 of the control) were detected after 2 weeks of diabetes." (PMID 23776493, 2013). "We show that short-term diabetes alters mRNA levels and axoplasm protein contents of kinesin family member KIF1A, KIF5B, KIF5A and Myosin Va in male but not in female rats." (PMID 29351809, 2018). "Nevertheless, no significant changes were detected neither in the levels of KIF1A in hippocampal total extracts, nor in its immunoreactivity in hippocampal subregions at 2 weeks of diabetes." (PMID 23776493, 2013). "Diabetes increased the expression and immunoreactivity of KIF1A and KIF5B in the hippocampus, but no alterations in dynein were detected." (PMID 23776493, 2013). "In this study, we found that there is an increase in KIF1A and KIF5B levels in the hippocampus at 8 weeks after the onset of diabetes, with no changes in dynein levels, suggesting that the anterograde transport may be impaired in the hippocampus." (PMID 23776493, 2013).
autism spectrum disorder (4 papers, 2017 to 2023). A spectrum of developmental disorders that includes autism, and Asperger syndrome. "KIF1A mutations are also linked to brain atrophy, encephalopathy, PEHO syndrome and autism spectrum disorder and all the disorders were observed to occur due to de novo variations in the KIF1A gene." (PMID 37259299, 2023).
axonal neuropathies (4 papers, 2010 to 2023). "KIF1A, a member of the kinesin family, appears to play a critical role in the development of axonal neuropathies resulting from impaired axonal transport." (PMID 20059769, 2010). "Given the mentioned KIF1A function, it may play a critical role in the development of axonal neuropathies resulting from impaired axonal transport." (PMID 37239332, 2023).
Cognitive impairment (4 papers, 2017 to 2023). Abnormal cognition is characterized by deficits in thinking, reasoning, or remembering. "Possibly, these mild cognitive impairments may be attributed to the KIF1A variants." (PMID 31488895, 2020). "However, mild cognitive impairment, such as learning difficulties, is relatively common in the general population and was also seen in some family members not having the KIF1A variant." (PMID 31488895, 2020).
microcephaly (4 papers, 2017 to 2022). A congenital or acquired developmental disorder in which the circumference of the head is smaller than normal for the person's age and sex. "Therefore, the alteration of FBXO11 and KIF1A could be associated with microcephaly and Guillain–Barré syndrome that develop during and/or after ZIKV infection." (PMID 35215967, 2022).
Parkinson disease (4 papers, 2022 to 2024). A progressive degenerative disorder of the central nervous system characterized by loss of dopamine producing neurons in the substantia nigra and the presence of Lewy bodies in the substantia nigra and locus coeruleus. "We report here the first patient with a KIF1A mutation resulting in SPG30 also with levodopa‐responsive parkinsonism, possibly indicating that this novel presentation results from nigrostriatal degeneration secondary to VMAT‐2 dysfunction." (PMID 37635774, 2023). "Of those, five patients presented MDs such as dystonia or parkinsonism, spasticity, and suspicion of brain iron deposits or GP hypointensities; they were associated with variants in FBXO7, FUCA1, GLB1, TPP1, and KIF1A." (PMID 36233161, 2022).
PEHO syndrome (4 papers, 2019 to 2023). PEHO (Progressive encephalopathy with Edema, Hypsarrhythmia and Optic atrophy) syndrome is a rare neurodegenerative disorder belonging to the group of infantile progressive encephalopathies. "All of the mutations implicated in PEHO syndrome, such as the T99M mutation, are found within the motor domain of KIF1A, suggesting that motor motility is impaired." (PMID 31616253, 2019). "Furthermore, a mutation exclusive to PEHO syndrome, E148D, presents with symptomology akin to complicated SPG-30, further suggesting that the etiology of these KIF1A-related disorders may be similar." (PMID 31616253, 2019).
Spastic paraparesis (4 papers, 2019 to 2021). Partial loss of the ability to move the lower limbs accompanied by spasticity of the lower limbs. "The mutation c.37C > T (p.(Arg13Cys)) in KIF1A was found in patient #19 with spastic paraparesis, behaviour disorder, slight enlargement of the interfolial spaces of the cerebellar hemispheres, hypertone and no craniofacial dysmorphisms." (PMID 34356170, 2021). "While, cases of mental retardation (MR) with neurological symptoms (mostly progressive spastic paraparesis) caused by autosomal dominant (AD) KIF1A mutations acquired de novo were reported more and more often starting from 2011." (PMID 32746806, 2020).
autosomal dominant spastic paraplegia (3 papers, 2018 to 2020). "More recently, variants in KIF1A have also been described in a few cases with autosomal dominant spastic paraplegia." (PMID 31488895, 2020). "In conclusion, KIF1A variants are a frequent cause of autosomal dominant spastic paraplegia in our cohort (6–7%)." (PMID 31488895, 2020). "The identification of KIF1A loss-of-function variants suggests haploinsufficiency as a possible mechanism in autosomal dominant spastic paraplegia." (PMID 31488895, 2020). "The motor domain of KIF1A is a hotspot for disease causing variants in autosomal dominant spastic paraplegia, similar to mental retardation type 9 and recessive spastic paraplegia type 30." (PMID 31488895, 2020). "KIF5A mutations account for autosomal dominant spastic paraplegia (SPG) 10, mutations in KIF1A lead to autosomal recessive SPG30 or to autosomal dominant cases of complex HSP and mutations in KIF1C have been found in autosomal recessive SPG58/SPAX2." (PMID 30067756, 2018).
Dystonia (3 papers, 2022 to 2025). An abnormally increased muscular tone that causes fixed abnormal postures. "Meanwhile, cases classified as “quite inconsistent” were mostly focal (n = 15) or segmental/multifocal (n = 8) dystonia and involved variants in genes typically associated with other disorders where dystonia is rarely reported, such as C19orf12, GRN, KIF1A, and PRKCG." (PMID 40533913, 2025). "While dystonia is not uncommon in KIF1A‐related diseases, this is the first report of patients without spasticity, potentially expanding the phenotypic spectrum." (PMID 40533913, 2025).
ovarian carcinoma (3 papers, 2022 to 2025). A malignant neoplasm originating from the surface ovarian epithelium. "High expression of the KIF1A gene in ovarian cancer is associated with a poorer prognosis, including shorter overall survival and post-progression survival." (PMID 41465326, 2025). "Specifically, studies have shown that ovarian cancer patients with higher KIF1A expression have a significantly reduced overall survival rate compared to those with lower expression." (PMID 41465326, 2025). "KIF1A expression is significantly increased in ovarian cancer tissues." (PMID 37719786, 2023). "Likewise, KIF1A expression negatively correlated with infiltration levels of 16 types of immune cells in ovarian carcinoma." (PMID 35359374, 2022). "This suggests that KIF1A could be a potential prognostic biomarker for ovarian cancer." (PMID 41465326, 2025).
Rett syndrome (3 papers, 2020 to 2023). A severe neurodevelopmental disorder affecting the central nervous system. "KIF1A mutations have been found in patients with a severe neurodevelopmental disorder with Rett syndrome patients." (PMID 37063368, 2023).
Alzheimer disease (2 papers, 2020 to 2024). A progressive, neurodegenerative disease characterized by loss of function and death of nerve cells in several areas of the brain leading to loss of cognitive function such as memory and language. "The manuscript “GSK3ß impairs KIF1A transport in a cellular model of Alzheimer’s disease but does not regulate motor motility at S402 “ characterizes the contribution of GSK3β on axonal transport in AD model." (PMID 33067366, 2020).